IL33 (interleukin 33)
Diseases named in the same sentence as IL33 in open-access papers (continued):
Sharing a sentence is not in itself a finding about the gene and the disease.
breast cancer (continued). "In contrast, IL-6, IL-1, and IL-33 can inhibit metastasis and mediate breast cancer cell death." (PMID 41596472, 2026). "Collectively, our study demonstrates that pregnancy blocks the age-associated imbalances in lineage integrity in the basal layer, including a decrease in Il33+ hybrid cells, that could potentially contribute to pregnancy-induced breast cancer protection." (PMID 41565642, 2026). "Collectively, these findings suggest that IL-33/ST2 signalling contributes to tumour progression across multiple breast cancer subtypes and may represent a therapeutic target beyond TNBC." (PMID 41284319, 2025). "The IL-33/ST2 signalling axis has multiple effects on breast cancer biology." (PMID 41284319, 2025). "Furthermore, stromal fibroblast-derived IL-33 has been shown to promote metastatic colonization in experimental breast cancer models by shaping a pro-metastatic immune microenvironment." (PMID 41284319, 2025). "Conversely, higher intratumoral expression of IL-33 may predict better response to chemotherapy or immune checkpoint inhibition therapy in some molecular subtypes of breast cancer." (PMID 41284319, 2025). "Similarly, IL33, which is enriched in the iCAF cluster of a murine breast cancer model, is also significantly increased during PBMC – CAF co‐culture." (PMID 39743376, 2025). "Similarly, flow cytometric analyses revealed time-dependent increase of IL-33 expression in mammary tumours during cancer progression." (PMID 41284319, 2025). "In this study, the levels of IL-33 and sST2 in patients with breast cancer were elevated compared to healthy subjects, consistent with the previous studies, suggesting that they play a crucial role in breast cancer development." (PMID 38585634, 2024). "Interleukin (IL)-33 is an important cytokine in the tumour microenvironment; it is known to promote the growth and metastasis of solid cancers, such as gastric, colorectal, ovarian and breast cancer." (PMID 38662248, 2024). "Fibroblast-derived IL-33 induces breast cancer progression by changing type-2 immunity." (PMID 39311766, 2024). "In addition, IL-33/ST2 signaling stimulates the dedifferentiation of malignant breast cancer cells, rendering the disease more aggressive." (PMID 37762328, 2023). "CAF-derived IL-33 induces type-2 inflammation as well as recruiting eosinophils, neutrophils, and inflammatory monocytes to the metastatic microenvironment, thus promoting breast cancer lung metastasis." (PMID 36635302, 2023). "Furthermore, our research indicates the pivotal role of the IL-33/ST2 pathway in promoting mammary tumor growth by upregulating pro-angiogenic VEGF expression in tumor cells and attenuating tumor necrosis." (PMID 37762328, 2023). "Induction or recombinant IL-33 enhances immune checkpoint blockade treatment in breast cancer." (PMID 37051596, 2023). "Moreover, increases in serum IL-33 levels appear to be more pronounced in advanced stage IV breast cancer, suggesting a role for IL-33 in disease severity and progression." (PMID 37762328, 2023). "A research reported that infusion of IL-33 is effective in suppressing lung metastases from mammary carcinoma in mice, which may be related to the elevation of NK cells at TME." (PMID 37153553, 2023). "Using a 4T1/LM4 breast cancer mouse model, we found that ILC2s were activated in both the micro- and macrometastatic regions, suggesting sustained activation throughout the metastatic cascades via IL-33/ST2 signaling." (PMID 35805039, 2022). "In addition, the fluorescence intensity of IL-33 was elevated in the metastases-bearing lungs and even more so in the primary mammary tumors." (PMID 35805039, 2022). "IL-33 has been shown to sustain MDSCs in human and mouse breast cancer, and there is some evidence that IL-33 may also affect MDSC recruitment in CRC." (PMID 36263033, 2022). "IL-33/ST2 signaling has been reported to promote breast cancer in several studies." (PMID 33946554, 2021).
breast cancer (continued). "In breast cancer, the level of tumoral IL-33 and ST2 was higher than in adjacent healthy tissue." (PMID 34209038, 2021). "In the present study, we demonstrated that the IL-33/ST2/COT/JNK1/2 signaling pathway could overexpress LPIN1 in breast cancer cells." (PMID 33946554, 2021). "Furthermore, JUN mediates the functions of some important cytokines in breast cancer, such as IL-34, IL-33, and IL-1β." (PMID 35127514, 2021). "In breast cancer, cholangiocarcinoma, and colon cancer, IL33 promotes cancer progression." (PMID 35011007, 2021). "In this study, we demonstrated for the first time that the IL-33/ST2 signaling pathway plays an important role in regulating LPIN1 expression, by enhancing the association of the c-Jun transcription factor with the LPIN1 promoter in breast cancer cells." (PMID 33946554, 2021). "Among eleven breast cancer samples with low IL-33, ten samples also showed lower LPIN1 expression." (PMID 33946554, 2021). "Furthermore, propranolol and SP600125, which are LPIN1 and JNK1/2 inhibitors, respectively, strongly suppressed IL-33-induced colony formation in breast cancer cells and mammary gland tumor development." (PMID 33946554, 2021). "In addition, we identified five ceRNA pairs (i.e., CDH5 with FAM212B, CDH5 with GYG2 in Module 45, TRIB1 with IL33, TRIB1 with INMT, and TRIB1 with MMRN1 in Module 110) that can be used as prognostic markers of breast cancer in BRCA-associated modules." (PMID 32256525, 2020). "IL-33 accelerates tumor growth and metastases of breast cancer and colorectal cancer." (PMID 30691509, 2019). "IL-33 was significantly higher in IGM patients as compared to breast cancer patients." (PMID 30205617, 2018). "In addition, in a mouse model of breast cancer, the administration of exogenous IL-33 resulted in the production of a mixed regulatory/Th2 immune infiltrate that promoted tumor growth." (PMID 30112116, 2018). "Serum levels of IL-33 were significantly higher in patients with breast cancer compared to patients with benign breast diseases, so the local expression of IL-33 may be a marker for differentiating malignant from normal/benign tissues." (PMID 30483263, 2018). "Moreover, IL-33 directly targets colon cancer cells and breast cancer cells via JNK-cJun activation, which promotes cell proliferation and therefore tumor growth." (PMID 30416507, 2018). "In 4T1 breast cancer model, IL-33 has been reported to promote MDSC expansion." (PMID 30483263, 2018). "In tumors with low levels of infiltrating Treg cells, administration of IL-33 accelerates tumor growth and occurrence of liver and lung metastasis in breast cancer mouse models, and these models display an intratumoral accumulation of MDSC and Treg cells, as compared to untreated mice." (PMID 30416507, 2018). "Furthermore, an increase in endogenous levels of IL-33 were observed in the 4 T1 model of breast cancer that correlated with cancer progression and metastasis." (PMID 29587679, 2018). "In patient-based studies, IL-33 expression correlated with breast cancer progression." (PMID 30205617, 2018). "Moreover, IL-33 also promoted the growth and metastasis of solid cancers, such as gastric cancer, colorectal cancer, ovarian cancer, and breast cancer." (PMID 30619376, 2018). "IL-33 facilitated endocrine resistance of breast cancer by inducing cancer stem cell properties." (PMID 29568370, 2018). "Local IL-33 expression may also increase intratumoral accumulation of immunosuppressive lymphoid cells in patients with breast cancer." (PMID 30483263, 2018). "We begin our discussion with breast cancer where the role of IL-33 in tumorigenesis was first identified, followed by colorectal cancer where many studies have been conducted, and then discuss each cancer based on their organ of origin and grouping according to the human organ systems." (PMID 30205617, 2018). "IL-33 is shown to promote tumorigenesis and induce stemness in breast cancer." (PMID 29285217, 2017).
breast cancer (continued). "Also, signaling through ST2/IL-33 on ILC2s during breast cancer has been shown to promote breast cancer growth and metastasis." (PMID 28484466, 2017). "IL-33 expression in mammary tumor cells significantly increased over time in WT mice, but not in IL-33R−/− mice, the findings that reflect positive feedback mechanism in IL-33/IL-33R axis." (PMID 26919112, 2016). "Therefore, the aim of this study was to investigate the role of IL-33/IL-33R axis in mammary tumor necrosis." (PMID 26919112, 2016). "Several studies point toward a pro-tumorigenic role of IL-33/ST2 signaling in breast cancer." (PMID 28119694, 2016). "In addition, we demonstrated that IL-33/IL-33R axis promoted breast cancer growth and metastases by facilitating intratumoral accumulation of immunosuppressive and type 2 innate lymphoid cells." (PMID 26919112, 2016). "In addition to these indirect pro-immunosuppressive mechanisms, IL-33 signaling appears to also blunt tumor surveillance in the murine 4T1 breast cancer model." (PMID 28119694, 2016). "Here, we report that IL-33/IL-33R signaling inhibits tumor necrosis in mouse mammary carcinoma." (PMID 26919112, 2016). "In the present study, we investigated whether serum IL-33 or sST2 correlated with VEGF levels or clinicopathological features in breast cancer tissues." (PMID 24636276, 2014). "Relationship of serum IL-33 levels with clinicopathological parameters of breast cancer patients." (PMID 24778632, 2014). "Moreover, the serum levels of IL-33 and sST2 in breast cancers significantly correlated with VEGF levels (IL-33: r = 0.375, P < 0.0001; sST2: r = 0.164, P = 0.045)." (PMID 24636276, 2014). "Clinicopathological analysis of cytoplasmic IL-33 expression in breast carcinoma." (PMID 24778632, 2014). "In this study, we aim to determine the serum level and to detect the expression of IL-33 in human tissues in patients with breast carcinoma, using Luminex-based measurements and immunohistochemistry, to further explore the role of IL-33 in anti-tumor immunity in BC." (PMID 24778632, 2014). "This could have negative consequences for the TME, as CAF‐derived IL33 has been associated with driving a type 2 inflammatory response and facilitating metastasis in lung metastasis of breast cancer." (PMID 39743376, 2025). "In addition to TNBC, recent studies suggest that IL-33/ST2 signalling may play a role in other breast cancer subtypes." (PMID 41284319, 2025). "Additionally, evidence has emerged indicating that IL-33 might influence breast cancer metabolism, especially by elevating Lipin-1 (LPIN-1) expression, a molecule involved in phospholipid metabolism." (PMID 37762328, 2023). "IL-33’s role in tumorigenesis was first identified in breast cancer, and more recently, omics studies and single-cell sequencing have demonstrated that, upon stimulation by IL-33 and IL-5 as well as CD4+ T cells, eosinophils could enhance CD8+ T-cell activation." (PMID 37296602, 2023). "Importantly, in light of this study's results, IL‐33 could represent an appealing treatment target in order to boost the effect of immunotherapy and possibly that of other therapies in breast cancer." (PMID 36892326, 2023). "Also, there are data that imply that, both in humans and mice, IL-33/ST2 signaling in breast carcinoma could induce stemness of a malignant cell, making it more challenging to treat with classic therapeutics, such as estrogen receptor inhibitors." (PMID 37762328, 2023). "Therefore, we suggest the possibility that primary mammary tumor–derived IL-33 may reach the lung through the bloodstream, promoting the proliferation and activation of ILC2s." (PMID 35805039, 2022). "Furthermore, we confirmed that IL-33 was released from both the metastases-bearing lungs and the primary mammary tumors, which might induce ILC2 activation." (PMID 35805039, 2022).
breast cancer (continued). "In particular, several studies reported that IL-33 and ST2 are implicated as potent modulators of the TME promoting immune cells recruitment and tumor malignancy in different types of cancer, including breast cancer, hepatocellular carcinoma, gastric cancer, and CRC31,57,58." (PMID 33953160, 2021). "In allogeneic transplantation and tumor environments, IL-33 could regulate the induction and migration of MDSCs to inhibit transplant rejection and promotes the progression of mouse breast cancer, the mechanism of which is related to its inhibition of T cell responses." (PMID 30863362, 2019). "Thus, serum levels of IL-33 and sST2 could serve as differential diagnostic markers between IGM and breast cancer along with radiological and pathological examinations." (PMID 30205617, 2018). "However, other researches considered IL-33 promoted cancer progression through diminishing innate anti-tumor immunity and increasing intra-tumor accumulation of immunosuppressive cells in transgenic mice with breast cancer." (PMID 30619376, 2018). "Thus, this study revealed an additional mechanism by which IL-33/IL-33R pathway may be involved in tumorigenesis and provide rationale for blocking IL-33 as a therapeutic modality in human breast carcinoma." (PMID 26919112, 2016). "Thus, the elevation of serum concentration of IL-33 or sST2 may be a valuable indicator of poor prognosis in breast cancer." (PMID 26456994, 2015). "In conclusion, IL-33 and sST2 may serve as noninvasive diagnosis markers for breast cancer." (PMID 26456994, 2015). "Thus, IL-33 may be a useful biomarker for prediction of malignant potential and immunosuppression of breast carcinomas." (PMID 24778632, 2014). "Preclinical studies have shown that simultaneous blockade of IL-33/ST2 and PD-1/PD-L1 enhances antitumor immunity and prolonging survival in murine breast cancer models." (PMID 41284319, 2025). "Future research should aim to elucidate the dual roles of IL-33/ST2 signalling and further understand how these roles change between breast cancer subtypes and disease stages." (PMID 41284319, 2025). "This review explores the synergistic potential of combining PD-1/PD-L1 blockade with IL-33/ST2 inhibition to overcome therapeutic resistance and enhance anti-tumour immunity in breast cancer." (PMID 41284319, 2025). "Dual blockade of PD-1/PD-L1 and IL-33/ST2 signalling pathways represents a novel and promising strategy to enhance the efficacy of immunotherapy in breast cancer." (PMID 41284319, 2025). "Co-blockade of the PD-1/PD-L axes and IL-33/ST2 axes shows promising results in reestablishing an effective immune response and offers a new perspective on improving immune response to breast carcinoma." (PMID 41096863, 2025). "Also, elevated IL-33 levels may accelerate breast cancer progression indirectly through signaling molecules like COT (Carcinoma Osaka Thyroid), which stimulate inflammation in the tumor microenvironment and foster the malignant transformation of the mammary epithelium." (PMID 37762328, 2023). "Another intriguing aspect of IL-33 involves its potential role in the differential diagnosis of idiopathic granulomatous mastitis (IGM) and breast cancer." (PMID 37762328, 2023). "Future research should aim to elucidate the intricate balance of pro-tumorigenic and anti-tumorigenic effects mediated by the IL-33/ST2 axis and to focus on how to harness this knowledge to improve the management of breast cancer." (PMID 37762328, 2023). "Doxorubicin drives breast cancer cells to induce IL-33, leading to the activation of Th2 T cells with abundant IL13 release through the IL-33/ST2 signal." (PMID 37173915, 2023). "The role of IL-33 and its receptor, soluble ST2, in estrogen receptor (ER)-positive breast cancer progression has been highlighted in extensive patient-based research." (PMID 37762328, 2023).
breast cancer (continued). "The IL-33/ST2 axis represents a dynamic and promising target in the field of cancer therapy, especially in the context of breast cancer." (PMID 37762328, 2023). "The role of the IL-33/ST2 axis in breast has been thoroughly studied, and there are much data obtained from both mice models and human breast carcinoma." (PMID 37762328, 2023). "In the present study, we showed that the IL-33-induced COT-JNK1/2 signaling pathway regulates LPIN1 mRNA and protein expression by recruiting c-Jun to the LPIN1 promoter in breast cancer cells." (PMID 33946554, 2021). "For instance, IL-33/ST2 signaling induces cancer cell stemness via the activation of JNK in human and murine colon cancer or the NF-kB pathway in breast cancer, promoting tumor growth." (PMID 34209038, 2021). "In contrast, five of the nine IL-33-high samples also had higher expression of LPIN1, indicating a positive correlation of IL-33 with LPIN1 levels in human breast cancer." (PMID 33946554, 2021). "In another study, a signature of four immune-related genes (APOD, CXCL14, IL33, and LIFR) was correlated with breast cancer prognosis." (PMID 33092068, 2020). "In breast cancer (BCA), IL-33 directly promoted ST2-positive BCA cell proliferation and colony formation via induction of the MEK-ERK, JNK-cJun and STAT3 signaling pathways." (PMID 33046978, 2020). "Well-designed tissue comparison assays showed an elevated IL-33 and IL1RL1 or ST2 in tissue of both human breast cancer and non-small-cell-lung cancer (NSCLC), compared to adjacent non-tumor tissues." (PMID 30619376, 2018). "The IL-33/ST2 signaling pathway, favoring pro-angiogenic VEGF expression in tumor cells and reducing tumor necrosis, is highly involved in mammary tumor growth." (PMID 30416507, 2018). "Orthotopically implanted 4T1 breast cancer cells showed a significant reduction in vascular endothelial growth factor (VEGF) and IL-33 expression as compared to tumors in wild type mice." (PMID 30205617, 2018). "Thus, the IL-33/ST2 pathway may represent an interesting target for breast cancer therapy." (PMID 28119694, 2016). "In breast cancer the 9p24 genomic amplicon contains six genes, among which ERMP1 and IL33 are overexpressed independently of the copy number increase, while GASC1, UHRF2, KIAA1432 and C9orf123 are overexpressed only in the context of gene amplification." (PMID 27566589, 2016). "IL-33 and ST2 expression are elevated in human breast cancer tissue compared to normal breast tissue." (PMID 28119694, 2016). "Interleukin-33 (IL-33)/IL-33 receptor (IL-33R, ST2) signaling pathway promotes mammary cancer growth and metastasis by inhibiting anti-tumor immunity." (PMID 26919112, 2016). "We analyzed expression levels of IL-33, IL-33R and VEGF in tumor cells in breast cancer tissues in two groups of patients." (PMID 26919112, 2016). "Stimulation with IL-33 enhanced proliferation as well as colony formation and size of a ST2-expressing breast cancer cell line." (PMID 28119694, 2016). "Deletion of IL-33R gene in mice favors tumor necrosis and decreases expression of IL-33 and VEGF in mammary tumors." (PMID 26919112, 2016). "Taken together, serum levels of IL-33, sST2, VEGF, MMP-11, and PDGF-C were higher in breast cancer patients than in healthy volunteers." (PMID 26456994, 2015). "Elevated expression of IL-33 was reported in colorectal cancer (CRC) tissues and serum of breast cancer and non-small cell lung cancer (NSCLC) patients." (PMID 26456994, 2015). "The serum levels of sST2, IL-33, and VEGF were significantly higher in breast cancer patients than in the control group (P < 0.05, each)." (PMID 24636276, 2014). "The serum levels of IL-33, sST2, and vascular endothelial growth factor (VEGF) in 150 breast cancer patients and 90 healthy women were measured by enzyme-linked immunosorbent assay." (PMID 24636276, 2014).